RN7SKP276 (RN7SK pseudogene 276)
Gene: Miscellaneous RNA gene on chromosome 1 (229,410,500 to 229,410,767, reverse strand). Ensembl gene ENSG00000252051.
Homologues: Orthologues: chimpanzee 7SK (92% identical). Paralogues in human: RN7SKP230 (64% identical), RN7SKP71 (63% identical), RN7SKP112 (62% identical), RN7SKP171 (62% identical), RN7SKP176 (62% identical), RN7SKP208 (62% identical), RN7SKP217 (62% identical), 7SK (62% identical), RN7SKP203 (62% identical), RN7SKP249 (62% identical), RN7SKP245 (61% identical), RN7SKP79 (61% identical), and 283 more.